PLXNB1 (plexin B1)
Diseases named in the same sentence as PLXNB1 in open-access papers (continued):
Sharing a sentence is not in itself a finding about the gene and the disease.
ovarian carcinoma (11 papers, 2010 to 2024). A malignant neoplasm originating from the surface ovarian epithelium. "The coexpression of MET and plexin-B1, the receptor of Sema4D, was associated with advanced-stage breast and ovarian carcinoma as indicated in MET/plexin-B1 double-positive tumors." (PMID 39742369, 2024). "In contrast, a recent study on human breast and ovarian cancers using immunohistochemistry showed that co-expression of Plexin-B1 and Met was significantly associated with a higher tumor grade and lymph node metastasis." (PMID 20858260, 2010). "In ovarian cancer, plexin-B1 was found to be upregulated in tumor tissues of patients as compared with healthy ovaries and to be in correlation with lymphatic metastasis." (PMID 37627074, 2023). "Knockdown of plexin-B1 in ovarian cancer-derived cells results in inhibition of AKT phosphorylation, re-arrangement of the actin cytoskeleton, and inhibition of tumor cell migration and invasion." (PMID 37627074, 2023). "The Plexin-B1 levels in the supernatants of the myeloma cell lines (76 ± 140 ng/ml) were decreased compared to the respective levels of the ovarian cancer cell lines (963 ± 1440 ng/ml, p = 0.008)." (PMID 29748532, 2018). "SKOV3 cells displayed the highest Plexin-B1 expression at both the mRNA and protein levels among the four tested human ovarian cancer cell lines and was selected as a cell model for further in vitro experiments." (PMID 21059203, 2010). "Although a recent study on human breast and ovarian cancers implies that Plexin-B1 functions as an oncogene when coupled with Met activation, involvement of ErbB-2 in this association has yet to be addressed in clinical studies." (PMID 20858260, 2010). "In addition, the impact of Plexin-B1 expression on ovarian cancer cell proliferation, migration and invasion were investigated in vitro." (PMID 21059203, 2010). "For example, the MEK/ERK signaling pathway, which was reported to be constitutively activated in epithelial ovarian cancer cells, has been shown to restore stress fibers in transformed fibroblasts, and a recent study suggested that Plexin-B1 can utilize RhoA to stimulate ERK." (PMID 21059203, 2010). "Plexin-B1 levels ranged from 15.00% in normal and benign ovarian tissues through 35.00% in borderline tumors to 55.00% in malignant ovarian tumors, suggesting that Plexin-B1 might be an early factor in ovarian serous tumor development." (PMID 21059203, 2010). "In addition, studies addressing whether this oncogenic function of Plexin-B1 in SKOV3 cells is a cell type-specific effect or instead is shared across multiple ovarian cancer cell lines are ongoing." (PMID 21059203, 2010). "Plexin-B1 expression was analyzed in normal and benign ovarian tissues and serous ovarian tumors (both borderline and malignant) by immunohistochemical staining, as well as in four human ovarian cancer cell lines (A2780, C13*, SKOV3, and OV2008) by RT-PCR and western blot analyses." (PMID 21059203, 2010). "We then characterized the expression of Plexin-B1 in several ovarian cancer cell lines, and SKOV3 showed highest level of Plexin-B1." (PMID 21059203, 2010). "At the individual cancer type level, we found that NRP2 and PLXNA2 were positively, while PLXNB1 and C1 were negatively correlated with ovarian cancer stemness score measured with DNAss, but not with RNAss." (PMID 32640719, 2020). "Interestingly, it was observed that VEGFR-2, plexin-B1, and Sema4D control the expression of CD31, MMP-2, and VE-cadherin in ovarian cancer cells, which are the markers and initiators of angiogenesis and VM." (PMID 31612116, 2019). "Regarding Plexin-B1, two myeloma cells lines (H929: 25.3 ng/ml and JJN3: 30.8 ng/ml) and two ovarian cancer cell lines (OVCA3: 5125 ng/ml and SKOV3: 3516 ng/ml) produced high levels compared to the other myeloma (4 ± 2.5 ng/ml) and ovarian cancer cell lines (27.6 ± 3.8 ng/ml)." (PMID 29748532, 2018).
cervical cancer (8 papers, 2012 to 2023). A primary or metastatic malignant neoplasm involving the cervix. "Plexin B1 (PLXNB1) is upregulated in cervical cancer tissue and HeLa cells, promoting cell proliferation, migration and invasion." (PMID 30563114, 2018). "For example, COS7 cells and cervical cancer cell lines express plexin-B1 and its ligand Sema4D, and thus Sema4D is likely to act in an autocrine manner to stimulate plexin-B1." (PMID 27656111, 2016). "Downregulation of miR-214 in cervical cancer has been reported by several groups, and miR-214 has been shown to inhibit the growth, migration, and invasion of cervical cancer cells by targeting oncogenes MEK3, JNK1, Plexin-B1, and GALNT7." (PMID 24614175, 2014). "MiR-214 has also been identified to be involvement of cervical cancer development by targeting MEK3, JNK1, GALNT7 and Plexin-B1." (PMID 24465927, 2014). "In cervical cancer, the ectopic expression of miR-214 could inhibit the proliferation, migration and invasive ability of HeLa cells by targeting MEK3, JNK1 and Plexin-B1." (PMID 22962603, 2012).
colorectal cancer (6 papers, 2016 to 2024). A primary or metastatic malignant neoplasm that affects the colon or rectum. "The immunohistochemical staining of colorectal cancer tissue specimens revealed that 95 (42 %) and 105 (46.4 %) of the specimens were positive for Sema4D and Plexin B1, respectively." (PMID 27456345, 2016). "Upregulation of Plexin-B1 is demonstrated on breast, pancreatic, and colorectal carcinoma tissues." (PMID 34337054, 2021).
head and neck squamous cell carcinoma (6 papers, 2010 to 2024). A squamous cell carcinoma that arises from any of the following anatomic sites: lip and oral cavity, nasal cavity, paranasal sinuses, pharynx, larynx, and salivary glands. "For instance, PLXNB1/SEMA4D promotes metastasis of head and neck squamous cell carcinoma by inducing epithelial–mesenchymal transition." (PMID 39443302, 2024). "Plexin-B1 transduces signals of sema4D (also known as CD100) in head and neck squamous cell carcinoma (HNSCC) in a xenograft mouse model." (PMID 37627074, 2023). "It has been reported that Sema 4D might exert its proangiogenic effect via Plexin-B1 to promote tumor growth and survival and thereby facilitate tumor metastasis in head and neck squamous cell carcinomas and other epithelial-derived tumors." (PMID 21059203, 2010). "Previous studies have shown that PLXNB1 can induce epithelial-mesenchymal transformation (EMT) and promote metastasis of head and neck squamous cell carcinoma, and NRP2 can promote tumor progression of thyroid papillary carcinoma." (PMID 36460803, 2023).
glioma (4 papers, 2015 to 2022). A benign or malignant brain and spinal cord tumor that arises from glial cells (astrocytes, oligodendrocytes, ependymal cells). "For example, SEMA3C mediates signalling via Plexin B1 in PCa whereas SEMA3C signals through Plexin D1 in glioma." (PMID 30759745, 2019). "Plexin-B2 protein was consistently detected at robust levels in all glioma samples; by contrast, Plexin-B1 and -B3 protein levels were highly variable between samples." (PMID 25762646, 2015). "The same group later found Plexin B1 also to be overexpressed in glioma cell lines." (PMID 35583632, 2022). "PLXNB1 influences amyloid beta load, and CIC is a transcriptional repressor whose inactivation promotes gliomagenesis, the formation of glial tumors in the brain." (PMID 33861770, 2021). "In contrast, our analyses did not reveal correlations of Plexin-B1 expression levels and glioma grade/type or patient survival, and only weak correlations for Plexin-B3 with lower Plexin-B3 levels corresponding to worse survival." (PMID 25762646, 2015). "In contrast, PLXNB1 and -B3 expression levels were highly variable between glioma samples, and on average not significantly different from levels in normal brain." (PMID 25762646, 2015). "Even though high immunoreactivity for Plexin-B1 has been reported in a subset of high-grade glioma, overall expression of Plexin-B1 or -B3 are not upregulated in gliomas, and their expression levels do not correlate with glioma grade nor patient survival." (PMID 25762646, 2015).
osteosarcoma (4 papers, 2016 to 2024). A usually aggressive malignant bone-forming mesenchymal neoplasm, predominantly affecting adolescents and young adults. "Sema4D and plexin-B1 is associated with osteosarcoma, in which PYK2-PI3K-Akt pathway is activated to promote tumor progression." (PMID 37096066, 2023). "Indeed, overexpression of Sema4D (along with Plexin-B1) is correlated with histological tumor type, TNM stage, and metastasis in prostate and colon cancers and a worse prognosis in both soft tissue sarcomas and osteosarcoma." (PMID 26910109, 2016).
bladder cancer (3 papers, 2018 to 2024). "Hence, we screened a panel of cells lines representing renal cancer (CAKI‐1, CAKI‐2, ACHN), bladder cancer (UC13, T24), and glioblastoma (U87MG), for expression of SEMA3C, EGFR, MET, Plexin B1, Plexin D1, NRP1, and NRP2." (PMID 29348142, 2018).
leukemia (3 papers, 2015 to 2022). A malignant (clonal) hematologic disorder, involving hematopoietic stem cells and characterized by the presence of primitive or atypical myeloid or lymphoid cells in the bone marrow and the blood. "Sema4D binding to plexin-B1 also stimulates the guanine nucleotide exchange factor (GEF) activities of PDZ-RhoGEF and leukemia-associated RhoGEF bound to the plexin-B1 C terminal PDZ-binding motif, which facilitates conversion of RhoA from the GDP-bound form to the GTP-bound from." (PMID 25351707, 2015).
lymph node metastasis (3 papers, 2010 to 2021). "Furthermore, the tumors with lymph node metastasis expressed higher levels of Plexin-B1 than those without lymph node metastasis." (PMID 21059203, 2010).
osteoporosis (3 papers, 2016 to 2022). A condition of reduced bone mass, with decreased cortical thickness and a decrease in the number and size of the trabeculae of cancellous bone (but normal chemical composition), resulting in increased fracture incidence. "Therefore, a pharmacological Plexin-B1 blockade in MS patients could potentially ameliorate both neuroinflammation as well as MS-associated osteoporosis." (PMID 35850304, 2022). "Next, we aimed to analyze the effects of the monoclonal anti–Plexin-B1 antibody RbPLX7 in in vivo models of osteoporosis and MS." (PMID 35850304, 2022). "Taken together, this work establishes a monoclonal anti–Plexin-B1 antibody as a novel potential pharmacological agent for the treatment of osteoporosis and MS." (PMID 35850304, 2022). "In summary, our data identify an anti–Plexin-B1 antibody as a potential therapeutic agent for the treatment of osteoporosis and multiple sclerosis." (PMID 35850304, 2022). "By employing a mouse line expressing human instead of endogenous murine Plexin-B1, we demonstrate that this anti–Plexin-B1 antibody exhibits therapeutic efficacy in preclinical models of osteoporosis and MS in vivo." (PMID 35850304, 2022). "Here, we describe the generation, characterization, and humanization of a novel monoclonal antibody directed against the transmembrane receptor Plexin-B1 that exerts therapeutic effects in mouse models of osteoporosis and MS with a mechanism distinct from all approved drugs." (PMID 35850304, 2022). "Given the pathophysiological importance of the Sema4D–Plexin-B1 interaction in mouse models of osteoporosis and MS, a pharmacological intervention to block their interaction could represent a promising therapeutic approach to treat osteoporosis and MS." (PMID 35850304, 2022). "Sema4D-/- mice demonstrate a mild osteosclerotic phenotype, identical to Plexin-B1−/− mice and mice expressing dominant-negative RhoA, so this signaling pathway could have therapeutic implications in diseases such as osteoporosis." (PMID 26910109, 2016). "In summary, we here describe the generation and characterization of an anti–Plexin-B1 antibody that specifically interferes with binding of Plexin-B1 to its high-affinity ligand, Sema4D, and validate its therapeutic efficacy in preclinical mouse models of osteoporosis and MS." (PMID 35850304, 2022). "As genetic deletion of Sema4D or Plexin-B1 results in elevated bone mass in mice by promoting osteoblastic bone formation without affecting osteoclastic bone resorption, pharmacological inhibition of Plexin-B1 could potentially add a new anabolic principle to osteoporosis treatment." (PMID 35850304, 2022).
renal cell carcinoma (3 papers, 2010 to 2022). "A possible mechanism underlying this expression status is that the Plexin-B1 gene is located in 3p21, which is a frequently deleted region in renal cell carcinomas." (PMID 21059203, 2010). "In renal cell carcinomas, Plexin-B1 was down-regulated and growth of cancer cells was inhibited." (PMID 21059203, 2010). "Similarly, Plexin-B1 expression is also down-regulated in renal cell carcinomas where 169 out of 209 carcinomas showed negativity in a recent report." (PMID 20858260, 2010). "For example, Plexin-B1 is absent in more than 80% of renal cell carcinomas but present in all kinds of renal tubules." (PMID 21059203, 2010).
asthma (2 papers, 2022 to 2023). "These residues are localized to the Sema4A-Plexin B1 interface and may participate in the Sema4A functions in an experimental model of asthma and in human Treg cell stability." (PMID 35328445, 2022). "Several other groups previously generated Plexin B1 KO mice, however they were not used to study the immune response or in models of immune mediated diseases such as asthma." (PMID 38259471, 2023).
cognitive decline (2 papers, 2023 to 2025). "In contrast, Rapid Decline showed increased β-amyloid (bA), glial and inflammatory markers (CD44, PLXNB1), and stress- and mitochondrial-related proteins (GSTP1, AK4, HSPB2, FBXO2, IGFBP5), which have been associated with neurodegeneration and cognitive decline in AD." (PMID 40799531, 2025).
dementia (2 papers, 2023 to 2024). Loss of intellectual abilities interfering with an individual's social and occupational functions. "Our findings included well-known dementia-associated protein biomarkers, such as BMP4, CD200, MANF, PLXNB1, PLXNB3, and SMPD1 for AD and BCAN, NCAN, and THY1 for VD, as well as uncovering novel proteins associated with AD or VD." (PMID 39226887, 2024).
diabetes mellitus (2 papers, 2022 to 2024). A metabolic disorder characterized by abnormally high blood sugar levels due to diminished production of insulin or insulin resistance/desensitization. "Taken together, our results suggest that diabetes mellitus impairs BMSCs differentiation and bone regeneration by decreasing the levels of miR-140-3p in BMSCs and exosomes, which lead to the increased expression of plexin B1 in vivo and vitro." (PMID 35236339, 2022). "Normal-Exos and miR-140-3p overexpressed-Exos accelerated diabetic wound healing by promoting the osteoblastogenesis function of BMSCs through inhibition plexin B1 expression which is the receptor of Sema4D and the plexin B1/RhoA/ROCK pathway compared with diabetes mellitus-Exos." (PMID 35236339, 2022).
glioblastoma (2 papers, 2015 to 2018). The most malignant astrocytic tumor (WHO grade IV). "In the TCGA glioblastoma samples, PLXNB2 expression was on average upregulated by more than 2.5-fold in classical and mesenchymal subtypes, and more than 1.5-fold in proneural and neural subtypes, while the expression levels of PLXNB1 and -B3 were largely similar between subtypes." (PMID 25762646, 2015).
lung carcinoma (2 papers, 2017 to 2023). "It has been reported that the expression levels of CD100, and one of its receptors, plexin-B1 (PLXNB1), are increased in head and neck, prostate, colon, breast, and lung cancers, and the interaction between them provides oncogenic signaling essential for tumor growth and metastasis." (PMID 28713384, 2017).
metastatic disease (2 papers, 2020 to 2023). "It is interesting to speculate that elevated levels of WT Plexin-B1 may suppress metastasis in a PTEN-deleted tumor, but if the Plexin-B1 acquires a mutation it may switch to a driver of aggressive metastatic disease." (PMID 36936664, 2023). "Interestingly, even the genes that showed no differential expression in tumors compared to normal samples also showed significantly increased (NRP2 and PLXNC1) or decreased (PLXNB1 and SEMA3F) expression in metastatic tumors (p < 0.0001)." (PMID 32640719, 2020).
multiple sclerosis (2 papers, 2020 to 2022). A progressive autoimmune disorder affecting the central nervous system resulting in demyelination. "Employing these mice, we demonstrate that the anti–Plexin-B1 antibody exhibits beneficial effects in mouse models of postmenopausal osteoporosis and multiple sclerosis in vivo." (PMID 35850304, 2022).
myeloma (2 papers, 2018 to 2021). "Regarding Plexin-B1, bone marrow plasma and serum levels were increased in myeloma patients compared to controls (44 ± 29 ng/ml vs. 3.4 ± 0.8 ng/ml, p < 0.01 and 11 ± 20 ng/ml vs. 2.6 ± 2.7 ng/ml, p = 0.01, for bone marrow plasma, and serum, respectively)." (PMID 29748532, 2018). "Thus, we evaluated Sema4D and Plexin-B1 in six myeloma cells lines in vitro; in the bone marrow plasma (BMP) and serum of 72 newly diagnosed symptomatic MM (NDMM) patients and in 25 healthy controls." (PMID 29748532, 2018).
rheumatoid arthritis (2 papers, 2020 to 2023). A chronic, systemic autoimmune disorder characterized by inflammation in the synovial membranes and articular surfaces. "Wang and associates assessed the significance of Sema4A-Plexin B1 pathway in the inflammatory response in rheumatoid arthritis (RA) by using human synovial fibroblasts of RA (RASFs) in in vitro cultures." (PMID 38259471, 2023).
allergic asthma (1 paper, 2023). A asthma with a basis in a pathological type I hypersensitivity reaction. "Our data indicate that Plexin B1 is critically involved in allergic asthma and plays a suppressor role in this disease in part by promoting and stabilizing Treg cells." (PMID 38259471, 2023). "We examined the response of WT and Plexin B1 KO mice to house dust mite (HDM), a common human allergen highly associated with allergic asthma and disease exacerbation." (PMID 38259471, 2023).
Alzheimer disease (1 paper, 2025). A progressive, neurodegenerative disease characterized by loss of function and death of nerve cells in several areas of the brain leading to loss of cognitive function such as memory and language. "Although PLXNB1 remains unexplored in PD pathogenesis, its protein function plays crucial roles in axonogenesis, cellular communication and cytoskeleton dynamics with activation of Ras-GAP domain via small GTPases in Alzheimer’s disease." (PMID 41327336, 2025).
B-cell chronic lymphocytic leukemia (1 paper, 2019). "SEMA4D/CD100 was found to be expressed in B-cell chronic lymphocytic leukemia (CLL) cells and in normal CD5+ B lymphocytes, and its high-affinity receptor Plexin-B1 was found in BM stromal cells, follicular dendritic cells, and activated T lymphocytes." (PMID 31143707, 2019).
basal cell carcinoma (1 paper, 2021). A carcinoma involving the basal cells. "To investigate a potential role of Plexin-B1 and Plexin-B2 for basal cell carcinoma progression in humans, we next studied primary human basal cell carcinoma cells." (PMID 33637728, 2021). "In line with this, we observed that expression levels of Plexin-B1 and Plexin-B2 in primary human basal cell carcinoma cells were low, and that re-expression of Plexin-B2 was sufficient to suppress YAP activity." (PMID 33637728, 2021).
benign ovarian neoplasms (1 paper, 2010). "In the present study, the expression levels of Plexin-B1 protein were found to be higher in serous ovarian carcinomas than in normal ovaries or benign ovarian neoplasms." (PMID 21059203, 2010).
breast tumor (1 paper, 2013). "In particular, plexin-B1 can function as an oncogene by promoting proliferation and survival of B-Cell Lymphoblastic Lymphoma cells and invasion of ovarian and breast tumor cells." (PMID 24009521, 2013).